MDK (midkine)
Diseases named in the same sentence as MDK in open-access papers (continued):
Sharing a sentence is not in itself a finding about the gene and the disease.
cancer (continued). "This ability of MDK to promote M2 polarization and macrophage infiltration has been demonstrated in several cancers, with several putative receptors being identified including LRP1, Notch2, and syndecan 3 (SDC3)." (PMID 40429950, 2025). "RNA interference (RNAi) and siRNA approaches effectively downregulate MDK expression, restoring chemosensitivity in resistant cancer cell lines such as gastric, lung, and leukemic models." (PMID 40500394, 2025). "As a growth factor, MDK contributes significantly to cancer progression and holds potential as a therapeutic target." (PMID 40777026, 2025). "MDK, a heparin‐binding growth factor, regulates crucial processes such as cell proliferation and angiogenesis in various cancers." (PMID 39910700, 2025). "Building on the body of literature characterizing MDK as a cancer-promoting protein, this review article will discuss the recent literature with a focus on the role and therapeutic implications of targeting the MDK axis to treat women’s cancers." (PMID 40429950, 2025). "MDK mediates cancer cell proliferation, survival, migration, and chemotherapeutic resistance via the PI3K/AKT and MAPK pathways." (PMID 40620228, 2025). "In preclinical investigations, the progression of numerous cancers has been impeded by the inhibition of MDK signaling through genetic knockdown or indirect inhibition of receptor signaling." (PMID 40429950, 2025). "The MDK signaling pathway demonstrated more complex communication patterns in high-riskscore cancer cells, establishing bidirectional signal exchange with hepatocytes." (PMID 41200185, 2025). "MDK is overexpressed in most cancer types and its overexpression drives the activation and metastasis of cancer cells through EMT." (PMID 40527884, 2025). "Midkine activates multiple cell-signaling pathways, with one of the pathways most commonly dysregulated pathways in cancers, including women’s cancers, being particularly affected." (PMID 40429950, 2025). "As such, future studies examining the utility of MDK inhibition in women’s cancers would be very beneficial." (PMID 40429950, 2025). "The diverse roles of MDK in immune modulation, angiogenesis, and multidrug resistance make it a key factor in the pathogenesis of both inflammatory diseases and cancer." (PMID 40500394, 2025). "Consistent with MDK’s ability to suppress cell death, evidence suggests that it also plays a role in preventing cell death in response to cancer therapies." (PMID 40429950, 2025). "By interacting with cell surface receptors and then activating the PI3K/AKT, STAT3, and MAPK/ERK pathways, MDK coordinates a series of signaling events that promote cancer cell stemness and cell proliferation." (PMID 40429950, 2025). "MDK expression in cancers can also be detected early, making it a relevant biomarker for cancer progression." (PMID 40527884, 2025). "s‐MDK levels increased with advancement in cancer stage and significantly increased in patients with high BSLD." (PMID 40620228, 2025). "In high ICDRS tumors, cancer cells exhibited more complex intercellular communication networks, establishing extensive signal exchanges with the microenvironment via MDK and MIF signaling pathways." (PMID 41200185, 2025). "Research indicates that MDK functions as an IF-γ response element, mediating IF-γ-induced metastasis across multiple cancer types." (PMID 40500394, 2025). "Targeted inhibition of MDK using iMDK can broadly reverse IFN-γ-activated EMT and eliminate the metastasis of various cancers caused by IFN-γ." (PMID 40527884, 2025). "One study found that MDK was better at predicting cancer than the conventional plasma markers (cancer antigen 15-3 (CA15-3), carcinoembryonic antigen (CEA), and NCCST-439 antigen) both alone and when combined." (PMID 40429950, 2025). "While MDK is elevated in most cancers, its link to estrogen signaling presents a notable connection between MDK and women’s cancers." (PMID 40429950, 2025).
cancer (continued). "In summary, these emerging studies suggest that MDK signaling contributes to the progression of women’s cancers." (PMID 40429950, 2025). "Considering the significance of MDK and its potential as an anti-cancer target, a small biotech company is developing MDK antibodies for clinical use." (PMID 40429950, 2025). "In contrast, low-riskscore cancer cells showed significantly reduced activity as MDK signal senders, indicating their limited capacity for actively regulating the microenvironment." (PMID 41200185, 2025). "Midkine has been repeatedly shown to enhance the vascular density and endothelial cell proliferation of tumors across various cancers." (PMID 40429950, 2025). "Therapeutic strategies aimed at silencing MDK expression—such as RNA aptamers and siRNA—have shown promise in preclinical models, with potential benefits in both cancer and chronic inflammatory diseases." (PMID 40500394, 2025). "Further analysis revealed that MDK and NCL/PTPRZ1/LRP1 were highly expressed in cancer cells and astrocytes/cancer cells/macrophages in the MDK signaling pathway, respectively." (PMID 40527884, 2025). "According to the authors, midkine (MDK) produced by carcinoma cells can engage nucleolin (NCL) receptors on adjacent stromal/endothelial cells." (PMID 40940815, 2025). "Elevated levels of MDK have been detected in blood and tissues of patients with several types of tumors, making MDK a potential cancer biomarker." (PMID 39300217, 2024). "In Nf1OPG mice, we elucidated a “neuron-immune-cancer cell” circuit, where T cells are induced by Nf1-mutant neuron-produced midkine to express Ccl4, which stimulates TAMs to secrete Ccl5, a key growth factor for Nf1-OPG development and progression." (PMID 38308315, 2024). "Collagens, MIF, MDK, APP, and laminin were the most highly expressed, and the top ligand-receptor interactions were CAF derived THBS2/THBS3 with cancer cell CD47, and CAF-derived MDK with cancer cell NCL/SDC2/SDC4." (PMID 38525245, 2024). "Of note, the PI3K/AKT signaling was one of the most important downstream pathways of MDK that exerted roles in cancer." (PMID 39014225, 2024). "In summary, in the present work, we report that BAG2, MAD2L1, and MDK are bona fide cancer-driver genes for MPM worth of further studies." (PMID 39300217, 2024). "MDK are known contributors to critical cancer hallmarks, including cell growth, metastasis and migration." (PMID 39187937, 2024). "There is also evidence that MDK serves as a mediator facilitating the acquisition of pivotal cancer hallmarks including metastasis, representing a potential treatment target." (PMID 39422697, 2024). "The inhibition of MDK is under consideration as a strategy for cancer therapy, and an inhibitor (iMDK) has been developed as an experimental molecule currently used in preclinical models." (PMID 39300217, 2024). "We summarize the current information on the involvement of MDK in drug resistance, and transcriptional regulators of its expression and highlight its potential as a cancer therapeutic target." (PMID 37240085, 2023). "Our results confirmed for the first time that miR-1275 inhibited epirubicin resistance via regulation of the miR-1275/MDK/AKT axis to lessen the properties of cancer stem cells, indicating that miR-1275 has potential to be a suppressor in BC chemoresistance." (PMID 36594100, 2023). "It is therefore conceivable that MDK is part of a common response mechanism to malignant tumors, and therefore potentially represents a central target for therapeutic intervention." (PMID 38098484, 2023). "The role of MDK in inducing drug resistance towards different conventional chemotherapeutic agents in different cancer types is discussed in the following section." (PMID 37240085, 2023). "While the potential of MDK as a biomarker has been proposed for several cancer types and inflammatory diseases, further studies are required to delineate its specificity as a biomarker." (PMID 38098484, 2023).
cancer (continued). "Midkine (MK), a cancer mediator that is highly expressed in a wide range of human malignancies, modulates cell growth, survival, migration, metastasis, and angiogenesis." (PMID 38235128, 2023). "MDK is highly expressed in various human malignancies and acts as a mediator for the acquisition of key cancer hallmarks, including cell growth, survival, metastasis, migration and angiogenesis." (PMID 36855810, 2023). "MDK, a secretory cytokine found in blood, can be exploited as a potent biomarker for the non-invasive detection of drug resistance expressed in various cancers and, thereby, can be targeted." (PMID 37240085, 2023). "Accumulated studies prove that midkine is involved in the malignant progression of cancers, including HCC." (PMID 36906597, 2023). "MDK mediates cell growth, survival, metastasis, and angiogenesis and accomplishes all the major hallmarks of cancer." (PMID 37240085, 2023). "Of note, among the ligands identified in SC-CM of all used cell lines, MDK aroused our interest as it is a neurite growth-promoting factor proposed to mediate metastasis in several cancer types 47–49." (PMID 37524695, 2023). "Midkine is rarely expressed by normal tissues, but significantly upregulated in inflammatory diseases and human malignant tumors." (PMID 36906597, 2023). "MDK promotes growth and invasion of cancers and can be an important cancer biomarker, aiding in the diagnosis and progression of several cancers." (PMID 37484982, 2023). "The frequency of cancer-cell (panCK+), as well as proliferating cancer cells (ki67+), was also reduced after MDK-inhibition in HN372 and HN380." (PMID 36973261, 2023). "MDK overexpression can be correlated with the diagnosis and disease prognosis in various cancers, and it can be a promising molecular target in personalized medicine." (PMID 37240085, 2023). "As expected, the majority of HN279 cancer cells expressed MDK, together with a number of genes associated with the pre-nodal phenotype (eg SNAI2, AXL, STAT2) that were unaffected by ICB." (PMID 36973261, 2023). "MDK is overexpressed in at least 20 different cancers compared to normal levels in healthy individuals." (PMID 37240085, 2023). "For cancer associated LR interactions from the immune-to-epithelial, the HGSOC patients had higher ITGA4_MDK and BTLA (to VTCN1 and TNFRSF14)." (PMID 38328306, 2023). "MDK is found to be highly expressed in various pathological conditions such as heart disease and cancer." (PMID 37484982, 2023). "Since MDK is an important mediator of tumorigenesis, attempts have been made to target it for cancer therapy." (PMID 37240085, 2023). "The heparin-binding growth factor MDK is a versatile oncoprotein well-reported in conferring cell proliferative and metastatic advantages in various cancers." (PMID 36672515, 2022). "MDK is a growth factor that acts on cancer progression and constitutes a potential therapeutic target." (PMID 36352420, 2022). "To further validate that MDK is necessary for cancer metastasis, we silenced MDK expression using a specific MDK inhibitor iMDK, which demonstrated high efficiency in decreasing endogenous MDK expression and subsequent EMT activation in all five cell lines." (PMID 35747815, 2022). "MDK is elevated in the majority of cancer types in the TCGA database, and its overexpression drove EMT activation and cancer metastasis in all examined cell lines." (PMID 35747815, 2022). "In The Cancer Genome Atlas (TCGA) database, we found MDK is the highest upregulated growth factor in different types of cancer, even higher than that of established growth factors such as VGF, EGF, and TGFB1." (PMID 35487917, 2022). "MDK expression was significantly upregulated in the cancer tissues compared to its expression in the adjacent normal tissues." (PMID 35487917, 2022). "It is worth noting that in TSS200 and TSS1500 regions, MDK is a critical player in cancer progression and immune microenvironment." (PMID 36727078, 2022).
cancer (continued). "iMDK decreased cell viability of the MDK-positive cancer cells in a dose-dependent manner, but less affected the MDK-negative cancer and non-transformed cells." (PMID 35747815, 2022). "Our data demonstrated that IFN-γ exposure resulted in a dramatic upregulation of MDK in all examined five cancer cell lines, suggesting this is a universal regulatory mechanism across cancers." (PMID 35747815, 2022). "The inhibitor iMDK is a small low molecular weight compound, demonstrating high efficiency and specificity in suppressing MDK expression in cancer cells." (PMID 35747815, 2022). "In line with its oncogenic role, MDK is elevated in the majority of cancer types in the TCGA dataset." (PMID 35747815, 2022). "Among the top CellChat interactions, we identified MDK from CAFs targeting SDC2/SDC4/NCL of cancer cells." (PMID 36352420, 2022). "Transwell assays clearly showed that MDK overexpression enhanced the migration and invasion capacities of all five cancer cell lines." (PMID 35747815, 2022). "For example, PTN (pleiotrophin) and MDK (midkine) are homologous ligands known to increase in response to inflammation and reported to influence many aspects of cancer biology, which are transcriptionally responsive to NF-κB." (PMID 36134665, 2022). "Taken together, MDK is highly expressed in most cancers, which suggests that MDK plays important functions in cancer progression." (PMID 35487917, 2022). "Our data demonstrated that STAT1 inhibition efficiently abrogated IFN-γ-induced MDK activation in all examined cancer cell lines, suggesting that the IFN-γ-MDK transduction is dependent on STAT1 in cancer." (PMID 35747815, 2022). "MDK was highly expressed in most cancer cell lines compared to its expression in immortalized normal human liver cells and mammary epithelial cells; however, in some cancer cell lines, MDK expression was almost negligible." (PMID 35487917, 2022). "The top outgoing signaling from epithelial cancer cells to CAFs (communication probability > 0.10) showed interactions between MIF (cancer cells) and CD74 + CD44 (CAFs) or MDK (cancer cells) and NCL/SDC2/LRP1 (CAFs)." (PMID 36352420, 2022). "Midkine (MDK), a secreted growth factor, regulates signal transduction and cancer progression by interacting with receptors, and it can be internalized into the cytoplasm by endocytosis." (PMID 35487917, 2022). "The expression of MDK has been reported to be upregulated in diverse types of cancer, which was confirmed in our study." (PMID 35487917, 2022). "Collagens, MIF, MDK, APP, and laminin were detected as the most significant signaling, and the top ligand-receptor interactions THBS2/THBS3 (CAFs)—CD47 (cancer cells), MDK (CAFs)—NCL/SDC2/SDC4 (cancer cells) as potential therapeutic targets." (PMID 36352420, 2022). "Here, we further indicate that MDK is also an IFN-γ inducible protein, which provides more insights into the MDK regulatory network in cancer." (PMID 35747815, 2022). "To further deep into the mechanism mediating IFN-γ-triggered EMT activation, we focused on MDK, which is a heparin-binding growth factor and an emerging oncoprotein well implicated in induction of EMT and cancer metastasis." (PMID 35747815, 2022). "We also found that MDK accelerates cancer cell proliferation by inhibiting the activation of the LKB1-AMPK axis." (PMID 35487917, 2022). "Taken together, these results indicate that MDK promotes the proliferation and tumorigenesis of human cancer cells." (PMID 35487917, 2022). "Taken together, these data showed that SRGN upregulates MDK expression in ESCC cells and promotes its secretion in a GAG-dependent manner, and that SRGN-induced MDK contributes to cancer cell invasion." (PMID 33456569, 2021). "MDK, a heparin‐binding growth factor, is strongly expressed in the majority of human malignant tumors." (PMID 34535962, 2021).
cancer (continued). "MDK (a cytokine and growth factor with complex biological functions involved in cancer development and progression), together with its two receptors (SDC1 and GPC2) were highly expressed in the B-cells of BCP-ALL samples." (PMID 33777800, 2021). "The MDK gene showed the most relevant increased expression in cancer tissues with a p value < 0.0001." (PMID 35008303, 2021). "MDK is a heparin-binding growth factor and acts as a mediator for the acquisition of critical hallmarks of cancer, including cell growth, survival, metastasis, migration, and angiogenesis." (PMID 33828969, 2021). "In this study, we have provided the first evidence of binding between glycosylated SRGN and MDK in cancer cells and explored its functional significance." (PMID 33456569, 2021). "MDK is involved in various cancer-related pathways, such as PI3K-Akt signaling, the cell cycle, and VEGF signaling." (PMID 34556138, 2021). "Our data also provide molecular insights into the potential role of Midkine in tumorigenesis, especially in regulating the cell cycle among cancer stem cells." (PMID 31882403, 2020). "In vitro experiments demonstrated that inhibition of Midkine successfully suppresses proliferation of cancer stem cells." (PMID 31882403, 2020). "In malignant tumors, Midkine promotes proliferation and metastasis and is also involved in CNS inflammation." (PMID 31882403, 2020). "MDK has been identified as a positive regulator of angiogenesis and is secreted by cancers to stimulate normal endothelial cell growth through paracrine signaling." (PMID 32847073, 2020). "CAF-derived midkine enhances ANRIL expression in cancer cells, which promotes cell proliferation and cisplatin resistance." (PMID 33050576, 2020). "Targeting the expression of MDK provides a new therapeutic approach for the treatment of MDK-expressing NSCLC patients and is useful in other types of cancers that express MDK." (PMID 32847073, 2020). "The cancer cell movement induced by MDK was significantly abrogated by siMDK since MDK-Notch2-NF-κB-Hes1 signaling was diminished by MDK knock down." (PMID 32847073, 2020). "Midkine is poorly expressed in the adult organism cells, while is highly incremented in cancer cells and correlated with a less favorable prognosis in cancer patients." (PMID 33414726, 2020). "Utilizing murine embryonic stem cells, human cancer-derived cell lines, and the embryonic retina in zebrafish, it has been established that Midkine can govern cell cycle kinetics." (PMID 32530962, 2020). "Heterogeneity of stem and progenitor populations is a clinical challenge when treating malignant tumors, where Midkine is highly expressed." (PMID 31882403, 2020). "HIF-1α has a dominant role in NSCLC via MDK expression, which promotes cancer cell progression and EMT through the Nothc2-NF-κB-Hes1 signaling axis through autocrine signaling and the migration of endothelial cells and vascuolization via a paracrine mechanism." (PMID 32847073, 2020). "In a cancer context, MDK has been proposed to promote resistance to anticancer treatments via ALK stimulation." (PMID 32308772, 2020). "Among the genes in our expression panel, MDK emerged as the most prognostic for cancer-specific survival." (PMID 31877738, 2019). "Although it has been widely studied in malignancies, the role of MDK in normal physiology has been investigated less extensively." (PMID 31648221, 2019). "In conclusion, this study shows that gene expression patterns in CTCs reflect the development of CRPC, and that MDK expression levels in CTCs are prognostic for cancer-specific survival in mHSPC." (PMID 31877738, 2019). "Versican expression is often correlated with high cell proliferation rates, particularly in cancer and has been shown to bind to the cell-cycle regulator Midkine." (PMID 30126423, 2018). "Among these, 15 articles were excluded (eleven detected the expression of MDK mRNA in cancer patients, two detected the expression of MDK in urine, two experiments were blurred)." (PMID 29872508, 2018).